CDKN2A (cyclin dependent kinase inhibitor 2A)
Diseases named in the same sentence as CDKN2A in open-access papers (continued):
Sharing a sentence is not in itself a finding about the gene and the disease.
pilocytic astrocytoma (15 papers, 2012 to 2024). Pilocytic astrocytoma is a rare subtype of low-grade glioma of the central nervous system characterized by a well circumscribed, often cystic, brain tumor with a discrete mural nodule and long, hair-like projections that extend from the neoplastic astrocytes. "For example, the identification of a BRAF fusion can lend credence to a diagnosis of histologically ambiguous pilocytic astrocytoma, or the presence of BRAF V600E mutation and deletion of CDKN2A/B gene by FISH or DNA testing can confirm the diagnosis of PXA." (PMID 38764578, 2024). "The only pilocytic astrocytoma with CDKN2A homozygous deletion showed a pejorative evolution with an OS of 60 months." (PMID 36900302, 2023). "Instead the association of CDKN2A expression with EFS events appeared to be associated with other diagnoses, mostly pilocytic astrocytomas." (PMID 36966348, 2023). "This case of a radiation-naive patient with pilocytic astrocytoma highlights how deletions of CDKN2A (cyclin-dependent kinase Inhibitor 2A) and PTEN (phosphatase and tensin homolog) portended a poor clinical outcome." (PMID 31355086, 2019). "Moreover, CDKN2A HD was detected in 1 out of 5 pilocytic astrocytomas (with pathologists’ p16 score of 1–2%)." (PMID 37138345, 2023). "The presence of CDKN2A and PTEN loss may be associated with aggressive biology in pilocytic astrocytoma and further studies should include comprehensive genomics in a larger series of adult pilocytic astrocytoma to evaluate this previously unreported finding." (PMID 31355086, 2019). "While these features align with the PD of PXA, the presence of necrosis and endothelial proliferation with no significant mitosis, the lack of CDKN2A/B deletion, and the MC of pilocytic astrocytoma made the final diagnosis a pilocytic astrocytoma." (PMID 37998600, 2023).
anaplastic astrocytoma (14 papers, 1997 to 2026). "Homozygous deletion at the CDKN2A/B locus at 9p12 was observed in the anaplastic astrocytoma UW479 line, which additionally harboured numerous high level copy number changes including 3p11-p12, 6p21, 18p11 and 19q12." (PMID 19365568, 2009). "Delaying treatment to wait for the molecular analysis (for instance IDH1-2 mutations results) could be detrimental for the patient, especially when the prognostic role of IDH1-2 status in HGG is debated, as described in recent studies which propose CDKN2A/B for anaplastic astrocytoma." (PMID 33798233, 2021).
metastatic carcinoma (14 papers, 2012 to 2025). A carcinoma which has spread from the original site of growth to another anatomic site. "Patients with APC+/CDKN2A- metastatic cancer survived significantly longer than the patients who are APC-/CDKN2A+ (median survival 52 months compared to 20 months, p < 0.0001)." (PMID 34204917, 2021). "Furthermore, when it came to metastatic cancers, patients with CDKN2A MU had even worse prognostic outcomes in four different tumor categories." (PMID 38822443, 2024). "Furthermore, when it came to metastatic cancers, we discovered that patients with CDKN2A ALT had even worse prognostic outcomes in 10 different cancer categories." (PMID 38822443, 2024). "In addition, another study showed that massively parallel sequencing coupled with dose-adjusted gemcitabine/carboplatin treatment of metastatic cancers with mutations in PDGFRA, SMAD4, and CDKN2A may lead to improved outcome." (PMID 32839457, 2020).
oropharyngeal squamous cell carcinoma (14 papers, 2014 to 2024). "Immunohistochemistry (IHC) staining for CDKN2A (p16) serves as a proxy for HPV status and is the leading prognostic biomarker in oropharyngeal squamous cell carcinoma." (PMID 37716475, 2023).
small cell lung carcinoma (14 papers, 2006 to 2024). Small cell lung cancer (SCLC) is a highly aggressive malignant neoplasm, accounting for 10-15% of lung cancer cases, characterized byrapid growth, and early metastasis. "Although it has been shown that cyclin dependent kinase inhibitor 2A (CDKN2A) plays a significant role in a number of malignancies, its clinicopathological value and function in small cell lung cancer (SCLC) is unclear and warrants additional research." (PMID 38206516, 2024). "Small cell lung cancer exhibited increased expression of MRP5, activation of Wnt pathway inhibitors, and upregulation of p38 MAPK activating genes, while NSCLC showed downregulation of CDKN2A, and upregulation of MAPK9 and EGFR." (PMID 16705311, 2006).
thymic carcinoma (14 papers, 2016 to 2026). Thymic carcinoma (TC) is a type of thymic epithelial neoplasm characterized by a high malignant potential. "The occurrence of CDKN2A mutations has been reported in approximately 11% of thymic carcinomas, demonstrating an association with diminished overall survival rates compared to wild-type counterparts." (PMID 37849766, 2023). "Encouragingly, CDK4/6 inhibitors represent a promising therapeutic approach for CDKN2A-mutated cancers, including thymic carcinoma." (PMID 37849766, 2023). "Recurrent CDKN2A alterations in TETs, mainly due to chromosome 16q loss in thymic carcinoma, as well as the upregulation of MYC/Max and E2F1, lead to hyperactivation of the CDK4-6/Rb pathway and subsequent cell cycle impairment." (PMID 36836670, 2023). "Previous studies reported the mutation frequency of CDKN2A in thymic carcinomas were 11%-35% and most of them were truncating mutation." (PMID 34307137, 2021). "This study confirmed that CDKN2A was a common mutation in the present cohort, with a frequency of 11.8% in thymic carcinomas, which was similar to that in previous studies." (PMID 34307137, 2021). "Twelve of 32 (38 %) analyzed thymic carcinomas exhibited a loss of the CDKN2A gene, which was heterozygous in three, homozygous in four and mixed heterozygous/homozygous in five cases." (PMID 27844328, 2017). "Moreover, inactivating mutations of CDKN2A have been described in thymic carcinomas, and p16INK4 expression can be suppressed by methylation of its promoter in thymic epithelial tumors." (PMID 38201593, 2023). "No specific GA was observed among the less frequent histopathological subtypes of thymic carcinomas that all presented with various frequencies of CDKN2A alterations." (PMID 35749302, 2022). "We and others have previously shown that 18 to 29% of thymic carcinomas also harbor homozygous deletion of CDKN2A." (PMID 35565429, 2022).
thymic carcinoma (continued). "Furthermore, we and others have shown that 18 to 29% of thymic carcinomas harbor homozygous deletion of CDKN2A." (PMID 35565429, 2022). "In 20 thymic carcinomas, results of our prior study of CDKN2A were available for comparison." (PMID 35565429, 2022). "In our study, however, CDKN2A gene loss or mutation did not correlate with a worse outcome in thymic carcinomas." (PMID 27844328, 2017). "We observed focal deletions of the CDKN2A and CDKN2B loci in thymic carcinomas and B3 thymomas." (PMID 38201593, 2023).
uveal melanoma (14 papers, 2000 to 2025). A melanoma derived from melanocytes of the uveal tract. "CDKN2A mutation rates were similarly low in uveal melanoma, with only one missense mutation (V28G within exon 1α) detected in the 80 uveal melanomas included in TCGA uveal melanoma cohort." (PMID 33076392, 2020). "Interestingly, germ line mutations in CDKN2A have been associated with familial melanoma syndromes and may have reflected genetic alterations from this patient’s uveal melanoma." (PMID 28302097, 2017). "However, approximately 32% of primary uveal melanomas and 50% of uveal melanoma cell lines show hypermethylation of the CDKN2A promoter, and this promoter methylation predominantly affected p16INK4a expression." (PMID 33076392, 2020). "High CDKN2A expression levels promoted natural killer cell-mediated cytotoxicity pathways in BRCA, OV and UVM (Uveal Melanoma)." (PMID 35004697, 2021). "Interestingly, CDKN2A expression was correlated with worse prognosis of patients with other cancers, including Adrenocortical Carcinoma (ACC), Colon Adenocarcinoma (COAD), Liver Hepatocellular Carcinoma (LIHC), Uterine Corpus Endometrial Carcinoma (UCEC), and Uveal melanoma (UVM)." (PMID 39914044, 2025).
fibrosarcoma (13 papers, 2009 to 2025). A malignant mesenchymal fibroblastic neoplasm affecting the soft tissue and bone. "Among these, CDKN2A loss stands out for its strong association with early recurrence and poor outcomes, especially in fibrosarcoma and MPNST." (PMID 40917595, 2025). "Other commonly CDKN2A-mutated tumors were myxofibrosarcomas (29.3%, n = 140), undifferentiated pleomorphic sarcomas (29%, n = 372), and fibrosarcomas (26.3%, n = 99)." (PMID 31528332, 2019). "For example, mice constitutively deficient for the tumor suppressor locus Cdkn2a (or Ink4a/Arf) are viable and fertile but develop fibrosarcomas and lymphomas." (PMID 25008045, 2014). "In the present study only exon 1β of CDKN2A was observed in LE's fibrosarcoma." (PMID 19643034, 2009).
Stroke (13 papers, 2009 to 2025). Sudden impairment of blood flow to a part of the brain due to occlusion or rupture of an artery to the brain. "To date, a stroke can be genetically associated with multiple susceptibility loci, including 9p21 (CDKN2A/CDKN2B/ANRIL), 7p21 (HDAC9), 6p21.1, 4p25 (PITX2), 16q22 (ZFHX3), 9q34 (ABO)." (PMID 33808851, 2021). "Other candidate genes include Interleukin-6 (IL-6) and CDKN2A/CDKN2B which have been implicated as sources of the racial disparities in stroke incidence." (PMID 34828431, 2021). "This locus harbors several genes including ANRIL, a long non-coding RNA gene implicated in the pathogenesis CVD and strokes, three candidate tumor suppressor genes; CDKN2A (cyclin-dependent kinase inhibitor 2A) encoding p16 protein, CDKN2B encoding p15 protein, and p14/ARF encoding p14ARF protein." (PMID 29765957, 2018). "Genetic variation at the CDKN2A locus also predicts stroke in hypertensive patients." (PMID 37265472, 2023).
diffuse large B-cell lymphoma (12 papers, 2015 to 2024). "Primary cutaneous diffuse large B-cell lymphoma of the leg type involves characteristic mutations in the MYD88 gene or CDKN2A deletions." (PMID 36291756, 2022). "The genetic test results of the left frontal parietal lobe lesion result revealed 23 gene mutations, including MYD88, CD79B, CDKN2A, PIM1, RELN, PCLO, CREBBP, and so on, supporting the diagnosis of diffuse large B-cell lymphoma." (PMID 36599976, 2023). "The result showed 23 gene mutations, including MYD88, CD79B, CDKN2A, PIM1, RELN, PCLO, CREBBP, and so on, supporting the diagnosis of diffuse large B-cell lymphoma." (PMID 36599976, 2023). "Damaging mutations in primary cutaneous diffuse large B-cell lymphoma of the leg type, involving MYD88 gene, or BCL6 and MYC translocations or CDKN2A deletions are useful for diagnostic purposes." (PMID 36291756, 2022). "ATRi (AZD6738) and WEE1i (AZD1775) display differential activity in a subpopulation of non-germinal-center-B cell (non-GCB) diffuse large B-cell lymphoma (DLBCL) cell lines characterized by high MYC oncogene expression and cyclin-dependent kinase inhibitor 2A/B (CDNK2A/B) deletion." (PMID 33167404, 2020).
hereditary pancreatitis (12 papers, 2013 to 2025). "With the following specific exceptions: individuals with Peutz-Jeghers syndrome (STK11 mutation) from 35 years of age, FAMMM (CDKN2A mutation) from 40 years of age and Hereditary pancreatitis (PRSS1 mutation) from 40 years of age." (PMID 38753287, 2024). "The study demonstrated a diagnostic-yield for FPC (3%), PRSS1/SPINK1 (hereditary pancreatitis; 4%), CDKN2A (FM) (5%), BRCA1/2 and PALB2 (HBOC) (6.3%), and STK11/LKB1 (Peutz–Jeghers syndrome; PJS; 12.2%)." (PMID 38619782, 2024). "Thus, germline mutations in the BRCA2, p16/CDKN2A, STK11, and PRSS1, that are responsible for familial breast cancer, Familial atypical multiple melanoma, Peutz-Jeghers and Familial pancreatitis, respectively, have been clearly associated with an increase risk of pancreatic cancer." (PMID 23935836, 2013). "This study also calculated the NNS for specific HRI groups, with a NNS of 250 for a PV in BRCA genes, 130 for PRSS1/SPINK1 (hereditary pancreatitis), 71 for STK11/LKB (PJS) and 51 for a PV in the CDKN2A gene." (PMID 38619782, 2024). "In addition, it is known that the mutation in CDKN2A (also known as P16) is correlated with familial atypical mole melanoma syndrome (FAMM); in STK11 (also known as LKB1), is correlated with Peutz–Jeghers syndrome; and in PRSS1 and SPINK1, correlated with hereditary pancreatitis." (PMID 36672301, 2023).
triple-negative breast carcinoma (12 papers, 2014 to 2024). An invasive breast carcinoma which is negative for expression of estrogen receptor (ER), progesterone receptor (PR), and human epidermal growth factor receptor 2 (HER2). "Of all ER/PR/ERBB2 triple-negative breast cancer patients, 7.5% possessed whole-gene deletions of CDKN2A, encoding the p16INK4a competitive inhibitor of Cdk4." (PMID 39095874, 2024). "She suffered from triple-negative breast cancer, and external panel sequencing of 94 genes that are associated with hereditary tumor disease detected a genetic pathogenic aberration in CDKN2A." (PMID 34680288, 2021). "CDKN2A is crucial in the immunotherapy of triple negative breast cancer (TNBC) and can be acted as a prognostic factor of TNBC." (PMID 36980514, 2023). "Contrastingly, for triple-negative breast cancer (TNBC), the phenotype EGFR was the best predictor at 0.78 followed by CDKN2A at 0.75." (PMID 37681908, 2023). "In order to underpin our finding on the triple negative tumor, we determined the methylation status of CDKN2A exon 2 in the triple negative breast cancer cell line MDA-MB-231 and compared it with that obtained for the luminal A cell line MCF-7 and the luminal B cell line ZR-75-1." (PMID 28403857, 2017).
anal carcinoma (11 papers, 2008 to 2024). "Our results suggest that transcriptional control exercised by the cyclin-dependent kinase inhibitor CDKN2A is inhibited in anal carcinomas." (PMID 18349847, 2008). "In cervical cancer, the same miR was also identified as a tumour suppressing molecule controlling p16(INK4A) or CDKN2A, which are well-known factors in anal cancer." (PMID 38899393, 2024). "Although the differences were only significant for CDKN2A/p16, the trend was consistent for all the genes evaluated, reinforcing the importance of HPV genotyping in anal cancer screening." (PMID 31684110, 2019).
cholangiocarcinoma (11 papers, 2018 to 2026). A carcinoma that arises from the intrahepatic biliary tree (intrahepatic cholangiocarcinoma) or from the junction, or adjacent to the junction, of the right and left hepatic ducts (hilar cholangiocarcinoma). "A recent genomic profiling analysis of cholangiocarcinoma harboring FGFR2 fusions or rearrangements showed that co-occurring CDKN2A/B alterations were associated with significantly shortened progression-free survival." (PMID 40013221, 2025). "In cholangiocarcinoma, miR-148a and miR-152 target DNMT1; reduced expression of these miRNAs contributes to increased DNMT1 activity, which affects transcription of the tumor suppressor genes Ras association domain family member 1 (RASSF1A) and cyclin-dependent kinase inhibitor 2A (p16INK4a)." (PMID 29401683, 2018).
gastric adenocarcinoma (11 papers, 2016 to 2025). "Analysis in stomach adenocarcinoma identified EBV-positive cases involving PIK3CA mutations and/or CDKN2A silencing with biologically more determination, compared to previous reports." (PMID 30837539, 2019). "Additionally, individuals with esophageal carcinoma or stomach adenocarcinoma who had CDKN2A MUT had poorer OS than patients from the MSK-IMPACT group, but not those with adenocarcinoma." (PMID 38822443, 2024). "Data analysis revealed a substantial correlation between LINC00460 and CDKN2A, implying that these two elements may be related to the survival and prognosis of patients with gastric adenocarcinoma." (PMID 37251440, 2023). "CDKN2A ALT, on the other hand, have the potential to be used as a biomarker for choosing patients for ICI treatment, notably in esophageal carcinoma and stomach adenocarcinoma." (PMID 38822443, 2024). "Cyclin‐dependent kinase inhibitor 2A (CDKN2A), a member of the cyclin‐dependent kinase inhibitors family, exerts its function by inducing cell cycle arrest in the G1 phase, while simultaneously exhibiting hypermethylation characteristics in gastric adenocarcinoma." (PMID 39184862, 2024).